TIGIT (T cell immunoreceptor with Ig and ITIM domains)
Diseases named in the same sentence as TIGIT in open-access papers (continued):
Sharing a sentence is not in itself a finding about the gene and the disease.
tumor (continued). "In addition to the typical expression of CD25, CD4, and FOXP3, Treg cells express a number of chemokine receptors and surface molecules, such as CTLA4, PD-1, and TIGIT, which are linked to anti-tumor immunity and may make them a direct target for ICI therapy." (PMID 35967424, 2022). "The fact that TIGIT expression is also associated with severely dysfunctional cytotoxic tumor-infiltrating T cells, and that their functionality was essentially restored in the absence of TIGIT in preclinical cancer models, serves as further evidence of TIGIT-mediated immunosuppression." (PMID 35327475, 2022). "Chronic antigen exposure, which characterizes the first part of tumorigenesis when tumor cells become detectable, stresses T cells, causing them to lose their effector function, become exhausted, and upregulate several immune inhibitor receptors (IRs) such as TIGIT." (PMID 35656508, 2022). "Besides, the level of tumor-infiltrating TIGIT+CD8+ T-cells have been remarkably associated inferior OS and relapse-free survival (RFS) of affected patients (HR = 2.17, 95% CI: 1.43–3.29, and p-value < 0.001, and HR = 1.89, 95% CI: 1.36–2.63, and p-value < 0.001, respectively)." (PMID 34638729, 2021). "TIGIT+CD3+ T cell infiltration was also greater in tumor tissue than in adjacent normal mucosa, and TIGIT overexpression correlated with tumor progression and adverse prognosis." (PMID 41596586, 2026). "First, TIGIT and CD155 are expressed on phenotypically and functionally diverse cell populations, including tumor cells, tumor-associated macrophages, NK cells, and multiple T cell subsets." (PMID 41596586, 2026). "In line with this, our cytokine analysis identified IFN-g as a shared positive associate of both TIGIT and CD155, which is consistent with the idea that immune activation and compensatory checkpoint upregulation can co-occur in tumor tissue." (PMID 41596586, 2026). "They demonstrated that the mean demethylation percentage of the TIGIT promoter in CRC tumor tissue was significantly higher than in non-tumor tissue." (PMID 41596586, 2026). "Before challenge with tumor cells, the expression of exhaustion-associated surface markers—including PD-1, TIM-3, LAG-3, TIGIT, and CTLA-4—was comparably low between iCD4+ and iCD8+ T cells." (PMID 41484912, 2026). "Immune checkpoint proteins including PD-1, CTLA-4, LAG-3, TIM-3, and TIGIT regulate T-cell functions, which are essential for anti-tumor immunity." (PMID 41681956, 2026). "PAX3, PAX5, and PAX8 are mainly associated with immune checkpoint expression, including PD-L1 and TIGIT, while PAX6 is linked to microsatellite instability and tumor mutational burden, implicating it in genomic dysregulation." (PMID 41752124, 2026). "Blocking TIGIT prevents NK cell exhaustion and boosts NK cell-mediated tumor immunity in various tumor-bearing mouse models." (PMID 40567374, 2025). "Re-expression of alternative immune checkpoints, such as LAG-3, TIM-3, and TIGIT, contributes to tumor immune escape and resistance to PD-1/PD-L1 blockade." (PMID 40361336, 2025). "We observed a significant difference in PD-L1/TIGIT co-expression in tumor-infiltrating cells from patients with triple-negative tumors compared to patients with Luminal A, Luminal B, and Her2+ tumors." (PMID 40565313, 2025). "By binding to its ligands, CD155 and/or CD122, TIGIT suppresses immune cell function, promoting tumor immune evasion." (PMID 40231264, 2025). "In tumor-infiltrating NK cells, TIGIT is highly expressed and its balance with DNAM-1 regulates NK cell cytotoxicity via PI3K-AKT-ERK phosphorylation cascades, thereby shaping the immune response." (PMID 40317077, 2025). "F. nucleatum uses the inhibitory receptor TIGIT, which is expressed on T cells, NK cells, and tumor-infiltrating lymphocytes (TILs), to evade immune detection." (PMID 39941737, 2025). "TIGIT was aberrantly co-expressed with PVRIG (4 of 4 tumor entities) and CD39 (2 of 4 tumor entities)." (PMID 40274631, 2025).
tumor (continued). "TIGIT blockade not only targets the anti-tumor effector T cell response, but also targets the induction of NK cell killing ability and regulatory T cell inhibition ability." (PMID 41186893, 2025). "In terms of HCC, tumor-resident Tregs express several immune checkpoints, including TIGIT and CTLA4, and the increased percentage of Tregs is closely related to the tumor stage and tumor size of HCC." (PMID 40186298, 2025). "Although TIGIT expression was notsignificantly different between normal and tumor sites in microsatellite instability (MSI)-low CRC patients, a relatively lower expression was still observed in normal tissues." (PMID 40799645, 2025). "Many preclinical studies have shown that the combination of an anti-TIGIT inhibitor and a PD-L1 inhibitor, results in superior tumor-killing effects compared with using PD-L1 inhibitors alone." (PMID 40783512, 2025). "Hafezi and colleagues developed a GMP-compatible protocol for efficient adenine base editing of TIM3 and TIGIT in tumor-infiltrating lymphocytes, resulting in enhanced expansion, cytokine production, and serial cytolytic capacity." (PMID 41394272, 2025). "Elevated TIGIT activity through interaction with CD155 affects tumor-specific CD8+ T cells, limiting TCR-induced p-ERK signaling, suppressing IFN-γ production, and NK-mediated cytotoxicity." (PMID 40584631, 2025). "Therapeutic resistance to TIGIT blockade can stem from tumor-intrinsic factors, such as low immunogenicity or poor antigen presentation, which limit T cell activation despite TIGIT inhibition." (PMID 40567374, 2025). "TIGIT expression has also been described as a poor prognostic marker in various tumor types, such as NSCLC or melanoma." (PMID 40508202, 2025). "Gene editing can also reinforce resistance to the suppressive tumor microenvironment by disrupting checkpoint regulators like PD-1, TIGIT, and TGF-β receptors, limiting tumor-mediated inhibition of NK cells." (PMID 40510336, 2025). "Our results align with previous findings from the previous mouse model, where the frequency of TIGIT+ CD8+ T cells was positively correlated with tumor burden, while the frequency of CD226+ CD8+ T cells showed a negative correlation." (PMID 39531203, 2025). "TIGIT was significantly upregulated in tumor-infiltrating immune cells in CRC, with predominant expression observed in exhausted CD8+ T cells (CD8+ Tex)." (PMID 40799645, 2025). "This indicates that TIGIT checkpoint inhibitors can play a role by reshaping the immunosuppressive tumor microenvironment." (PMID 40129984, 2025). "In tumour-infiltrating NK cells, it was shown that TIGIT is upregulated, leading to an inhibitory phenotype of the cells." (PMID 40317320, 2025). "Our results suggest that memory CD8 + T cells “remember” tumour antigens, leading to potent immune reactions that suppress tumour regrowth in all challenged animals previously treated with anti-PD-1 and anti-TIGIT antibodies." (PMID 39939955, 2025). "Prolonged exposure to both tumor and microbial antigens intensifies TIGIT expression in NK cells, accelerating the shift towards a depleted NK cell phenotype, which diminishes their ability to combat tumors." (PMID 40027183, 2025). "In all tumor types, TIGIT methylation showed a significant correlation with the infiltration of monocytes and/or neutrophils, with at least one or both cell types being affected (p < 0.05)." (PMID 40076932, 2025). "The engagement of TIGIT by NECTIN3 on tumor cells results in the functional impairment of both T cell subsets, thereby reducing their ability to mount an effective anti-tumor response and promoting tumor immune evasion." (PMID 41007114, 2025). "T cells from patients with early relapse exhibited higher TIGIT expression than those from patients with durable responses, and elevated TIGIT levels were correlated with increased tumor burden and poor prognosis." (PMID 41419632, 2025).
tumor (continued). "Along this line, a low baseline level of PD-L1 and TIGIT by tumor cells has been reported in patients with large B-cell lymphoma who have shown a better response to CAR T cells." (PMID 40973766, 2025). "Circulating TIGIT+CD8+ T cells were tumor-specific, with TIGIT+PD-1+ cells (co-expression) displaying greater activation and differentiation than single-positive cells." (PMID 40944710, 2025). "TIGIT attenuates NK-cell-mediated tumor immunity by reducing cytotoxicity and impeding cytokine production, such as IFN-γ." (PMID 40567374, 2025). "Tumor growth was notably slower, and tumor weight significantly lower in the anti-TIGIT-treated mice in comparison to the control group (P < 0.05)." (PMID 39939322, 2025). "In contrast, TIGIT expression followed an opposite trend, with reduced levels in the tumor compared to the liver in both ILC1-like and cNK cells, as well as in total NK cells." (PMID 41268557, 2025). "CD226highCD8+ T cells exhibit greater responsiveness and self-renewal at tumor sites, and anti-TIGIT treatment enhances their function by promoting CD226 phosphorylation." (PMID 40723878, 2025). "Anti-TIGIT therapy alone has demonstrated favorable results only in certain melanoma cell lines, with the combination with radiotherapy being able to control tumor growth in these models." (PMID 40277786, 2025). "First, F. nucleatum can interact with the human inhibitory receptor TIGIT through its protein Fap2, thereby suppressing the tumor-killing activity of NK cells." (PMID 41473772, 2025). "In line with the metastatic situation, we and others recently detected expression of co-regulatory molecules including TIGIT on M2-like macrophages derived from tumor tissue." (PMID 40274631, 2025). "The anti-tumor efficacy of co-targeting TIGIT and PD-1/PD-L1 using individual mAbs against these ICs has been demonstrated by several trials." (PMID 40890162, 2025). "Another emerging strategy involves checkpoint-integrated multispecific antibodies that simultaneously target tumor antigens and inhibitory pathways such as PD-1 or TIGIT." (PMID 40508128, 2025). "TIGIT+ B cells can influence immune-infiltrative structures to drive tumor progression, whereas MALT-B cells activate the complement pathway, thereby boosting anti-tumor immunity." (PMID 40469295, 2025). "Is it known that in colon cancer cell, Fap2 of F. nucleatum binds the human immune receptor named “T-cell immunoreceptor with Ig and ITIM domains” (TIGIT), present on Tumor-Infiltrating Lymphocytes (TILs)." (PMID 41011327, 2025). "TIGIT is highly expressed on tumor-infiltrating lymphocytes, and blocking TIGIT together with PD1 markedly enhances CD8 T cell activity." (PMID 41177809, 2025). "There are no known data about the correlation of RNA modifications and TIGIT, but many studies have confirmed that RNA methylation regulates tumor immune evasion." (PMID 40565233, 2025). "Concurrently, TIGIT inhibits NK cell degranulation, cytokine production, and the cytotoxicity of NK cells against tumor cells expressing CD155." (PMID 40356928, 2025). "TIGIT and PD-1 are co-expressed on tumor-infiltrating lymphocytes (TILs) in both human and experimental murine cancers." (PMID 39847233, 2025). "The increased expression of TIGIT also enhances the suppressive function of regulatory T cells (Tregs), further impairing anti-tumor immunity." (PMID 39941737, 2025). "Surprisingly, in addition to CTLA-4, anti-TIGIT inhibitors can also synergistically inhibit tumor growth in immunocompetent mice." (PMID 41236411, 2025). "Regulatory T cells (T regs) emerged as key contributors to the suppressive tumor microenvironment, with the highest average mRNA expression of the inhibitory molecule TIGIT." (PMID 40703802, 2025). "TIGIT signalling thus establishes an immunosuppressive microenvironment favorable for tumour survival and metastasis." (PMID 40777027, 2025).
tumor (continued). "More importantly, animals treated with anti-PD-1 and TIGIT antibodies showed an increase in immune-infiltrated lymphocytes per tumour weight as well as the number of CD107a + CD8 + T cells and their ratio to CD4 + /Foxp3 + regulatory T cells within the tumour." (PMID 39939955, 2025). "Immune checkpoints such as PD-1/PD-L1, CTLA-4, LAG-3, TIM-3, and TIGIT play critical roles in regulating anti-tumor immunity and are exploited by hematological malignancies to evade immune surveillance." (PMID 40723175, 2025). "The bacterial surface protein Fap2 interacts with the inhibitory receptor TIGIT expressed on natural killer (NK) cells and cytotoxic T lymphocytes (CTLs), leading to the suppression of anti-tumor cytotoxic responses." (PMID 41465299, 2025). "In preclinical studies, the nectin-4 and TIGIT interaction inhibited natural killer cell activity, and nectin-4 blocking antibodies enhanced tumor cell killing." (PMID 40225697, 2025). "scRNA-seq analysis of immune checkpoints within tumor-infiltrating T cells revealed significantly higher TIGIT expression in T cells from the ER patient compared to DR patients (P < 0.05)." (PMID 41419632, 2025). "The binding of CD226 to its ligand CD155 promotes an antitumour immunity response, while TIGIT competitively interacts with CD155 to induce tumour-immune invasion." (PMID 41462864, 2025). "TIGIT is frequently co-expressed with PD-1 in tumor-infiltrating immune cells across various cancers, including esophageal cancer." (PMID 40567374, 2025). "To evaluate the therapeutic potential of TIGIT blockade, we examined its dose-dependent effects on the tumor-killing ability of NK cells." (PMID 40231264, 2025). "Although the absolute frequencies were lower than those of the PD-1+TIGIT+ and PD-1+Tim-3+ populations, the relative increase within the tumor remained substantial (HD: 1.0%; treatment-naïve: 1.5%; treated: 1.7%; TILs: 5.3%)." (PMID 41300994, 2025). "Overexpression of TIGIT in cancer cells or tumour-infiltrating stromal cells typically predicts poorer OS and is linked to pathological grading and lymph node metastasis." (PMID 40994140, 2025). "Although the absolute number of CD8+ T cells in combination treated tumours is lower than the PI3Kγ monotherapy group, they are more cytotoxic with elevated expression of granzyme B, perforin and TIGIT, indicating a checkpoint-engaged phenotype." (PMID 39788719, 2025). "In various tumor models, TIGIT blockade not only prevents NK cell dysfunction but also enhances antitumor immune responses through NK cell-mediated mechanisms." (PMID 40463500, 2025). "Further studies on the role of immune checkpoints, including PD‐1/PD‐L1, TIM‐3, LAG‐3, and TIGIT, in the tumor microenvironment are needed to explore their potential as therapeutic targets." (PMID 40347011, 2025). "In preclinical models, the dual PD-1/TIGIT blockade has been shown to provide the additive expansion and functional activity of tumor antigen-specific CD8+ T cells and TILs." (PMID 40508202, 2025). "Further enrichment of TILs in the tumour microenvironment was observed in animals treated with anti-PD-1 and anti-TIGIT contributing to the robust response rate and long-term overall survival." (PMID 39939955, 2025). "This study reveals a role of NLRP4 in shaping a distinct anti-tumor microenvironment, driven by NKomega (TIGIT+TNFA+ NK cells) and M1omega (iNOS+ M1 macrophages)." (PMID 40087771, 2025). "Tumour-bearing mice were i.p. injected with different combinations of anti-PD-1, anti-TIGIT, and anti-CTLA-4 antibodies at a dose of 0.2 mg/mouse, respectively." (PMID 39939955, 2025). "The combination of TIGIT blockade and metabolic reprogramming has shown enhanced anti-tumor responses in preclinical models of solid tumors, including CCA." (PMID 41394868, 2025). "The mechanism of amplification of the irradiation benefit is CD8+ T cell-dependent, with TIGIT blockade promoting tumor infiltration with DCs and activation of CD8+ T lymphocytes." (PMID 40277786, 2025).
tumor (continued). "TIGIT expression was increased on tumor-infiltrating conventional T cells and Tregs compared with T cells from matched blood." (PMID 41364531, 2025). "In particular, TIGIT is involved in the control of antitumor immunity mediated by tumor-infiltrating microbes." (PMID 40038799, 2025). "The identification of additional co‐inhibitory receptors, including emerging immune checkpoints like LAG‐3, TIM‐3 and TIGIT, is advancing anti‐tumour immunotherapy development." (PMID 40415479, 2025). "In MMRd tumors, resistance following anti-PD-1 treatment is driven by the expression of TIM3, LAG3, CTLA4, and TIGIT by TILs, as well as tumor clonal selection and the expression of TREM2, CSF1R, IFITM, TMEM176B and IL1B by myeloid cells." (PMID 40027748, 2025). "For example, in tumor bearing mice models, TIGIT+ NK cells acquired an exhaustion phenotype, with reduced effector function and antitumor potential." (PMID 40236693, 2025). "TIGIT is a co-inhibitory receptor mainly expressed on T cells and NK cells and has been found to be highly upregulated in tumor-infiltrating lymphocytes (TILs) in melanoma and other cancers." (PMID 41181119, 2025). "CD155 is overexpressed in many cancers, which can be utilized by this approach to target and kill tumor cells through the fusion of TIGIT’s extracellular domain (ECD) with intracellular stimulatory domains." (PMID 40890162, 2025). "In the tumor microenvironment, Tregs expressing a higher level of TIGIT display a more immunosuppressive and activated phenotype." (PMID 39847233, 2025). "OAd-SIRPα-Fc and OAd-Siglec10-Fc have been shown to significantly suppress tumor growth in macrophage-rich tumor microenvironments, while OAd-TIGIT-Fc primarily enhances T cell activation." (PMID 40698086, 2025). "TIGIT is highly expressed on human and murine immune cells infiltrating several tumor types where it negatively regulates anti-tumor responses by binding CD155 or CD112, which are widely expressed on tumor cells." (PMID 39706891, 2025). "The tumor microenvironment was highly immunosuppressive, characterized by enrichment with PD-1, PD-L1, and TIGIT; TIGIT was notably upregulated in locally advanced versus early-stage tumors." (PMID 41300994, 2025). "Altogether, we delineated NLRP4’s unexplored facets and discovered an NLRP4-driven anti-tumor ecosystem composed of TIGIT+TNFA+ NK and iNOS+ M1." (PMID 40087771, 2025). "A recent in-depth mechanistic study revealed that an anti-TIGIT antibody enhances PD-L1 blockade, facilitating the shift of anti-tumor CD8 + T cells from an exhausted effector-like state to a more memory-like state through myeloid and Treg cells." (PMID 39847233, 2025). "Tregs in tumour tissue exhibit elevated TIGIT expression compared with those in peripheral lymphoid organs, exhibiting a high activity and inhibitory phenotype, effectively limiting anti‐tumour immunity." (PMID 40415479, 2025). "As the hTIGI7.11E has an affinity for human TIGIT only, the investigators tested its anti-tumor effect in the MC38 tumor-bearing model of TIGIT humanized mice." (PMID 40890162, 2025). "Research indicates that the upregulation of TIGIT and LAG-3 is closely associated with immune evasion and tumour resistance." (PMID 40861435, 2025). "We identified the expression of immune checkpoint protein CD155 on MB tumor cells and the expression of its inhibitory binding partner TIGIT on immune cells of MB patient-derived tissues, cell lines, and PDX MB organoids." (PMID 40703802, 2025). "To validate these findings in vivo, we administered anti-TIGIT mAb to A20 tumor-bearing Rag2-/- mice following the experimental scheme." (PMID 40231264, 2025). "These TIGIT+ Tregs were found to suppress anti-tumor immune responses, and IL-32 was shown to promote BC cell migration and invasion, contributing to metastasis." (PMID 40177538, 2025).